LNX1 (ligand of numb-protein X 1)
Diseases named in the same sentence as LNX1 in open-access papers (continued):
Sharing a sentence is not in itself a finding about the gene and the disease.
tumor (12 papers, 2015 to 2023). "We further show that this upregulation results in a functional increase in stemness within the tumor, and that reduction in LNX1 levels is associated with decreased stemness and improved outcomes in animal models." (PMID 33255632, 2020). "Given that LNX1 regulates Notch signaling, which can further induce expansion of the GSC niche, we hypothesized that elevations in LNX1 during TMZ therapy could be associated with increases in overall stemness of the tumor population." (PMID 33255632, 2020). "PR−/ER− cases demonstrated frequent loss of LNX1 and SNORA80A, and gain of ZNF4, STK24 and CCDC191; gain of CDK20 was common in PR-high tumours." (PMID 34079052, 2021). "Our data suggest that LNX1 is the important regulator of the cell cycle, and contributes to tumor progression." (PMID 34439220, 2021). "Having observed that LNX1 elevations are indeed associated with the induction of a stem-like state, we wanted to assess the effect of overexpression of LNX1 on the “stemness” of the tumor cell population in the differentiation media." (PMID 33255632, 2020). "LNX1 assists the tumor-suppressive function of LDOC1 by mediating the targeted degradation of activated JAK2 (pJAK2), and resultantly, interferes in the IL-6/JAK2/STAT3 signaling axis." (PMID 33333989, 2020). "We further showed that the elevation of LNX1 and Notch1 results in an increase in the tumor stem cell population, a subpopulation of cells thought to help propagate a more aggressive tumor." (PMID 33255632, 2020). "LNX1 knockdown increased the number of cancer stem cells and led to the formation of more colonospheres in extreme limited dilution assays, and more tumours in mice injected with LNX1 knockdown HT29 cells." (PMID 32714586, 2018). "The sections were then scored for LNX1 presence within the tumor body." (PMID 33255632, 2020). "Overall, this supports our hypothesis that knocking down LNX1 results in a significant decrease in stemness, which can result in a less aggressive tumor." (PMID 33255632, 2020). "Overall these findings suggest that LNX1 may act as a tumour suppressor and that up-regulating LNX1 expression may represent a novel therapeutic strategy to negatively regulate cancer stemness in CRC." (PMID 32714586, 2018). "Effect of LNX1 knockdown on the tumor formation rate using the HT29 cell line." (PMID 29190716, 2017). "Using only experimentally verified PPIs, LNX1 (Ligand of Numb-Protein X, an E3 ubiquitin-protein ligase) was discovered as hub-gene and a sub-network of six keratins was shown to be upregulated in all miliary tumor cell types." (PMID 25991672, 2015). "This represents another potential mechanism by which LNX1 might promote tumour formation." (PMID 32714586, 2018). "Moreover, knockdown of LNX1 decreased the tumor formation rate in vivo." (PMID 29190716, 2017).
tumor (continued). "PPI network analysis revealed these genes and modules were mainly related to tumor progression (LOXL1, IKBKE, LNX1, FOXA2, FGF17, and FGF2) and immune response (STAT4, IL23R, LTA, ITK, and IL19)." (PMID 36611170, 2023). "Among these genes, SPINT2, LNX1, FOXA2, and SOSTDC1 were reported to be related to tumor progression, whereas TYROBP, TREM2, IL23R, CSF2RB, TRAF1, and TGFBR1 were closely associated with immune response." (PMID 36611170, 2023). "The top genes in cold tumor are ARF1, PDIA3, ALDOA, FKBP2, NDUFS5, NDUFC1, COX7A2, C14orf2, LNX1, and BTBD6." (PMID 33816503, 2021).
cancer (6 papers, 2017 to 2025). A tumor composed of atypical neoplastic, often pleomorphic cells that invade other tissues. "LNX1 has been shown to contribute to cisplatin resistance by regulating cell cycle progression in human cancer cells." (PMID 35267540, 2022). "In a previous study, we reported that LNX1 acts as an oncogene and found that the expression levels of LNX1 increased in cancers using the TCGA database." (PMID 34439220, 2021). "The aim of the present study was to elucidate the regulation of LNX1 expression and clarify the role of LNX1 in cell-cycle progression and resistance to the cancer therapeutic agent, cisplatin." (PMID 34439220, 2021). "As LNX1 expression induced the cell cycle, we sought to determine its role in cancer therapy using cisplatin." (PMID 34439220, 2021). "Here the authors observed that LNX1 mRNA and protein were down-regulated in a population of putative cancer stem cells (side population cells) isolated from the CRC cell line HT29." (PMID 32714586, 2018). "Knockdown of LNX1 mRNA expression in HEK cells using siRNA led to cell cycle arrest and caused alterations in the expression levels of several cancer associated genes." (PMID 32714586, 2018). "In this study, LNX1 was identified as a negative regulator of cancer stemness in CRC, which was downregulated in colonospheres or side population (SP) cells." (PMID 29190716, 2017). "To investigate the molecular mechanisms of the inhibition of cancer stemness mediated by LNX1, we screened potential substrates of LNX1 using RNAi and the SP analysis." (PMID 29190716, 2017). "Here our results indicate that LNX1 suppresses cancer stemness which partially requires the downregulation of CXADR." (PMID 29190716, 2017). "It is noteworthy however that this region contains a number of potentially cancer promoting receptor tyrosine kinase encoding genes (c-KIT, PDGFR-α and VEGFR2) and so amplification of LNX1 may be incidental." (PMID 32714586, 2018). "This suggested that LNX1 is a negative regulator of cancer stemness in CRC." (PMID 32714586, 2018). "Here in this article, LNX1 was first identified as a negative regulator of cancer stemness in CRC and we showed that targeting LNX1 could provide a promising strategy against CSCs for clinical CRC research." (PMID 29190716, 2017). "Furthermore, the coxsackievirus and adenovirus receptor (CXADR) was found to be one critical downstream mediator of cancer stemness regulated by LNX1." (PMID 29190716, 2017). "Although several studies indicate LNX1 could be a potential suppressor of cancer diseases, the functions of LNX1 in mediating cancer stemness remain poorly understood." (PMID 29190716, 2017). "Based on the Dual-Luciferase Reporter system of LNX1 promoter, we screened different drugs in an attempt to find out a small molecule that could suppress cancer stemness via targeting LNX1." (PMID 29190716, 2017). "Interestingly, it was observed that tamoxifen downregulated the transcriptional activity of LNX1 and suppressed cancer stemness." (PMID 29190716, 2017). "In addition, we need to confirm the role of LNX1 in various other cancer cell lines and in vivo." (PMID 34439220, 2021). "LNX1 knockdown leads to increased CAR protein levels, suggesting that CAR may be involved in mediating the effect of LNX1 on cancer stemness, although the mechanism by which LNX1 regulated CAR levels and whether it involved LNX1-mediated ubiquitination of CAR was not examined." (PMID 32714586, 2018).
cancer (continued). "Thus, LNX1 could be a potential drug target in cancer therapy against colorectal CSCs." (PMID 29190716, 2017). "As the overexpression of LNX1 decreased cisplatin-induced cell death in HEK293 cells, we examined whether LNX1-overexpressing cancer cells were resistant to cisplatin treatment." (PMID 34439220, 2021). "The ligand of numb-protein X1 (LNX1) is reported to be upregulated in various cancers, however the cellular function of LNX1 is not clearly characterized." (PMID 34439220, 2021).
infection (2 papers, 2017 to 2020). The state of being infected such as from the introduction of a foreign agent such as serum, vaccine, antigenic substance or organism. "Infection with gamma-irradiated M. tuberculosis prevented the expression of LNX1 in both types of macrophages." (PMID 32487755, 2020). "Transfection of miR-325-3p or infection with gamma-irradiated M. tuberculosis can also downregulate LNX1, resulting in the accumulation of NEK6 in macrophages." (PMID 32487755, 2020). "In accordance with the upregulation of miR-325-3p during infection with gamma-irradiated M. tuberculosis, dual-luciferase assay and real-time quantitative PCR (qRT-PCR) were used to detect the transcription of Lnx1 in response to stimulation with gamma-irradiated M. tuberculosis." (PMID 32487755, 2020).
infectious disease (2 papers, 2018 to 2020). A disorder directly resulting from the presence and activity of a microbial, viral, or parasitic agent in humans. "A recent finding showed that LNX1 suppressed the aggravation of tuberculosis, an infectious disease caused by Mycobacterium tuberculosis." (PMID 33333989, 2020). "In specific studies, LNX1 and LNX2 were shown to be associated with infectious diseases, including Kawasaki disease and Q fever." (PMID 33333989, 2020). "A couple of studies have found associations of LNX1 and LNX2 with infectious diseases." (PMID 32714586, 2018).
LNX1 also shares sentences with these, for which no sentence is quoted: hyperekplexia (1 paper); neurological diseases (1).